INS (insulin)
Diseases named in the same sentence as INS in open-access papers (continued):
Sharing a sentence is not in itself a finding about the gene and the disease.
Cognitive impairment (continued). "Preclinical evidence has shown that intranasal insulin may also ameliorate cognitive deficits in 6-hydroxylase dopamine (6-OHDA)-induced rat models of PD by regulating the Akt/Glycogen Synthase Kinase 3 Beta (GSK3β) signaling pathway." (PMID 37893474, 2023). "Clinical findings indicate that insulin and leptin resistance are related to cognitive deficits and neuropsychiatric disorders, and interestingly, these analyses propose that the associated deficits in neuroplasticity can be reversed by restoration of insulin and leptin sensitivity." (PMID 36674935, 2023). "Development of the intranasal insulin treatment has led to multiple human clinical trials demonstrating increased brain cell energy in healthy adults and improved memory in healthy adults and individuals with mild cognitive impairment or AD." (PMID 35631378, 2022). "Oral antidiabetics and insulin seem able to reduce cognitive impairment in AD." (PMID 35203654, 2022). "Furthermore, ICV-STZ has now been found to induce cognitive impairment and neuron damage, oxidative stress and glucose/energy metabolism damage in the brain, insulin resistance in the brain, and finally lead to Tau hyperphosphorylation and Aβ deposition." (PMID 35741643, 2022). "As might be expected, cognitive impairments in schizophrenia are related to brain insulin resistance, supporting its role in the pathophysiology of cognitive dysfunction in SZ." (PMID 36483840, 2022). "It indicated that IR might serve as a precursor to cognitive disorders and intranasal insulin might become a potential therapy to hinder cognitive function decline." (PMID 35873818, 2022). "Several studies have also explored the effect of intranasal insulin on improving memory deficits in patients with AD or MCI (mild cognitive impairment) clinically in humans, and these clinical data consistently indicate the positive effects of intranasal insulin on cognitive function in patients." (PMID 36430894, 2022). "In addition, delivery of insulin to targeted brain tissues has been proposed as a potential strategy for treating cognitive impairment in DM patients." (PMID 36407319, 2022). "Liraglutide has been investigated in animal experimental models, as well as in randomized controlled trials, with promising results, showing increases in brain insulin signaling, and a possible effect on mental scale scores of patients with mild cognitive impairment." (PMID 35453527, 2022). "Moreover, post-mortem studies have demonstrated central insulin signaling dysregulation in hippocampal and cortical samples from patients with both mild cognitive impairment and early AD." (PMID 35406040, 2022). "Thus, there is a need to identify the factors that contribute to the disruption in insulin signaling and metabolic pathways and determine how these contribute to cognitive impairment in PWH." (PMID 35720083, 2022). "Therefore, disturbed brain insulin signaling can greatly affect cognitive impairment and neurodegeneration, particularly mild cognitive impairment and AD." (PMID 34070553, 2021). "It is plausible that brain insulin resistance contributes to cognitive deficits in schizophrenia." (PMID 34108878, 2021). "Conversely, insulin-sensitizing strategies have been shown to improve memory performance, reduce cerebrospinal fluid biomarkers of disease, and enhance cerebral glucose utilization in mild cognitive impairment (MCI) and AD patients (Hölscher, 2014)." (PMID 34512303, 2021). "In addition, promising therapeutic interventions, especially current advances in anti-diabetic agents targeting the insulin pathway to alleviate cognitive impairment in AD and schizophrenia were also summarized." (PMID 34108878, 2021). "Past clinical studies have also shown that intranasal insulin therapy may exert a therapeutic effect on AD patients and on patients with mild cognitive impairment." (PMID 34671194, 2021).
Cognitive impairment (continued). "In recent months, the first multicenter, randomized, double-blind (phase 2/3) clinical trial evaluating the feasibility, safety and efficacy of intranasal insulin in the treatment of patients (ages 55 to 85) with mild cognitive impairment and dementia in AD was released." (PMID 34068096, 2021). "These remarkable effects were comparable with that produced by pioglitazone, which was proven to diminish cognitive impairment along with neuronal preservation via enhancement of insulin signaling, in addition to displaying antioxidant and anti-inflammatory activities." (PMID 34366841, 2021). "Therefore, intranasal insulin administered before anesthesia induction can prevent the development of anesthesia-related behavioral and cognitive impairment." (PMID 33799976, 2021). "In addition, intranasal insulin treatment can alleviate AD pathogenesis and cognitive impairment via reduced neuroinflammation and enhanced neural plasticity, possibly via the actions through receptors on microglia and astrocytes." (PMID 34795562, 2021). "Indeed, experimental evidence suggests the link between impaired insulin signaling in the CNS and cognitive impairment." (PMID 34795562, 2021). "Intranasal insulin treatment for 6 weeks could decrease anxiety-related behaviors, ameliorate cognitive deficits, enhance the impaired brain insulin signaling, alleviate of Aβ pathology and promote neurogenesis." (PMID 34108878, 2021). "Also, the extract increased the hippocampal level of glutathione (GSH), SOD and glutamate receptor expression and prevented from cognitive impairment and insulin resistance in diabetic rats." (PMID 33628721, 2021). "In these scenarios, the interplay between inflammation and insulin resistance could represent a potential therapeutic target to prevent or ameliorate neurodegeneration and cognitive impairment." (PMID 33967682, 2021). "The extent to which disrupted insulin transport into the brain or any of the individual molecular mechanisms described contribute to cognitive impairment and insulin resistance in the brain compared to any of the other mechanisms is unknown." (PMID 33845179, 2021). "SCZ is conceptualized as an illness of dopaminergic dysfunction, links to abnormal metabolism (particularly type II DM), and may share plausible overlaps with CNS insulin dysregulation because of premorbid cognitive deficits." (PMID 34690937, 2021). "The disruption of insulin action in the brain is considered as a potentially important pathophysiological mechanism of cognitive impairment via deficits in neuronal structure and function, impaired synaptic plasticity, brain mitochondrial dysfunction, increased oxidative stress and inflammation." (PMID 34108878, 2021). "Indeed, ICV-STZ mice develop neuroinflammation, amyloidogenesis, tau hyperphosphorylation, brain insulin resistance and cognitive impairments, just as reported to occur in human brains of affected subjects." (PMID 34830036, 2021). "In addition, in a feline HIV model in vivo, intranasal insulin enhanced the preservation of cortical neurons and improved cognitive performance, suggesting that impaired insulin signaling in the CNS may underlie cognitive impairment in HIV positive individuals." (PMID 34795562, 2021). "Although the original causes for cognitive impairment in AD and schizophrenia are somewhat different, similar disturbances in glucose metabolism and insulin signaling will undoubtedly have further negative impact on the cognitive function of both disorders." (PMID 34108878, 2021). "The aim of this study is to determine whether exogenous insulin, evaluated by daily insulin requirement, has an impact on mild cognitive impairment (MCI), and whether this relationship is mediated by insulin doses and other risk factors." (PMID 34577866, 2021). "The results from this study, we found Ori could improve cognitive impairment and insulin sensitivity in MHE rats." (PMID 31568638, 2020).
Cognitive impairment (continued). "Moreover, metformin improves insulin sensitivity and decreases fasting insulin levels in cognitive impairment patients with abnormal glucose metabolism." (PMID 32425881, 2020). "Moreover, damaged insulin signaling in the brain can greatly affect cognitive impairment and neurodegeneration, particularly mild cognitive impairment and AD." (PMID 32083135, 2020). "We recently discovered that intranasal administration of insulin, which can bypass the blood-brain barrier and deliver insulin directly to the brain, can prevent anesthesia-induced brain changes and cognitive impairment in adult and aged mice." (PMID 31354415, 2019). "These disturbances of insulin action can directly contribute to cognitive impairment and even AD." (PMID 31440156, 2019). "In general, being female, a low level of education, rural residence, smokeless tobacco consumption, unhealthy eating habits, insulin use, history of CAD, and cognitive impairment were associated with inadequate glycaemic levels in the Bangladeshi T2DM population." (PMID 31308457, 2019). "The crosstalk between impaired insulin transmission and cognitive impairment may also be evidenced by benefits from intranasal insulin administration in patients with AD." (PMID 30781611, 2019). "Here, we hypothesized that a7nAChR loss in hippocampus is involved in “CAP” deficit, and excessive inflammatory response may lead to insulin signaling inactivation and cognitive impairment in DM rats." (PMID 31551793, 2019). "Second, weak muscle strength and cognitive impairment may share common pathophysiological pathways such as systemic inflammation, insulin resistance and oxidative stress, all of which may contribute to both weak muscle strength and cognitive impairment." (PMID 30249201, 2018). "Taken together, miR-200b/c may contribute to reduce Aβ secretion and Aβ-induced cognitive impairment by promoting insulin signaling." (PMID 29738527, 2018). "A large clinical trial is under way to test whether different types of insulin improve memory when administered intranasally to patients with mild cognitive impairment or early AD (ID: NCT01767909)." (PMID 29435980, 2018). "CNS administration of insulin into the brain can attenuate these cognitive impairments." (PMID 30619085, 2018). "The present study examined the nature of hippocampal-dependent memory impairments in a mouse model of DIO and whether direct chronic insulin administration into the CNS could counteract these cognitive impairments mechanistically by reducing neuroinflammation." (PMID 30619085, 2018). "AD is associated with brain insulin resistance, leading to the possibility that the insulin-sensitizing properties of adiponectin may confer protection in AD and other cognitive disorders." (PMID 30150999, 2018). "Appropriate dosage and administration of insulin is crucial, and optimal insulin treatment might be especially difficult among people with concomitant cognitive impairment." (PMID 29337859, 2018). "Hence, intranasal insulin probably helps the prevention of anesthesia-induced cognitive impairment through several molecular pathways." (PMID 28539885, 2017). "Overall, these initial findings suggested that increased β -cell function/insulin secretion is associated with cognitive impairment, at least in non-demented adults." (PMID 28852028, 2017). "Thus, our findings suggest that three daily doses of intranasal insulin can prevent both the short-term cognitive impairment and long-term neurobehavioral changes induced by anesthesia." (PMID 28539885, 2017). "Given that IGF-1 is a key partner of the actions of insulin, insulin levels may also influence the disease cognitive impairment." (PMID 27627435, 2016). "Insulin concentration post glucose loading has also been associated with cognitive impairment as well as AD among the subjects who do not carry ApoE4 allele." (PMID 27642517, 2016).
Cognitive impairment (continued). "We recently found that general anesthesia disturbs brain insulin signaling and induces abnormal hyperphosphorylation of tau24, which might contribute to the anesthesia-induced cognitive impairment." (PMID 26879001, 2016). "However, a few clinical trials using intranasal insulin administration have reported successful cognitive outcomes in AD or mild cognitive impairment patients." (PMID 30202553, 2016). "It is possible administration of daily intranasal insulin for less than seven days may be sufficient to prevent anesthesia-induced cognitive impairment." (PMID 26879001, 2016). "We therefore hypothesized that administration of insulin into the brain may prevent anesthesia-induced brain changes and cognitive impairment." (PMID 26879001, 2016). "More importantly, we were eager to learn whether the insulin pretreatment can prevent anesthesia-induced cognitive impairment." (PMID 26879001, 2016). "In general, providers do not recognize the administration of medication as a potential barrier to adherence, except in the case of patients with physical or cognitive impairments, co-morbid conditions, or related to treatments, for example fear of needles upon initiation of insulin treatment." (PMID 26596271, 2015). "Based on the results of cognitive testing, female SHRs were further used to investigate whether cognitive deficits are accompanied by alterations of insulin signaling in the brain, when compared to WKY controls." (PMID 26110057, 2015). "This hypothesis was further strengthen when intracerebroventricular administration of streptozotocin resulted in AD-like cognitive impairments, neurodegeneration and insulin resistance." (PMID 26136647, 2015). "The different changes of insulin signaling in AD and in these models might represent a diversity of insults, which might ultimately contribute to cognitive impairment." (PMID 24575038, 2014). "In addition, the beneficial effects of intranasal insulin or GLP-1 administration to patients with mild cognitive impairment or T2DM have to be considered." (PMID 25346723, 2014). "Thus pramlintide treatment probably should be considered at least in diabetic patients who need insulin treatment and suffer from cognitive impairment." (PMID 25750761, 2014). "Insulin and leptin resistance has been related to the dysregulation of energy balance and to the induction of a chronic inflammatory status which have been recognized as important cofactors in cognitive impairment and AD initiation and progression." (PMID 22701480, 2012). "A third novel observation in our study relates to gender-specific differences in insulin sensitivity and cognitive performance, with males apparently exhibiting a greater adiposity, weight gain, glucose dysregulation and cognitive impairment compared to females." (PMID 22509243, 2012). "Furthermore, APP+ -ob/ob mice had more pronounced cognitive impairment, despite having similar insulin levels." (PMID 21070531, 2010). "In addition, daily intranasal insulin treatment has been shown to lessen cognition impairment in patients diagnosed with early AD." (PMID 21044348, 2010). "Moreover, examining the interaction effects of lifestyle factors, such as smoking and dietary habits, on the insulin resistance-cognitive impairment relationship could guide more personalized preventive strategies." (PMID 40538401, 2025). "This suggests that the cognitive impairment of AD mice may be related to the insulin signaling pathway, and DSS intervention may reduce the accumulation of neuropathological products by regulating the IRS1/GSK3β/Wnt‐β‐catenin pathway, thus playing a cognitive protective role." (PMID 39344343, 2024). "Notably, insulin treatment (Group L + I) significantly ameliorated cognitive deficits, increasing time spent in the target quadrant (30.03 ± 1.39%, #p < 0.05 vs. Group L) and the frequency of entries into the target location (2.58 ± 0.26, #p < 0.05 vs. Group L) during probe trials." (PMID 39073013, 2024).
Cognitive impairment (continued). "Therefore, dysregulation of insulin signaling pathways may trigger cognitive impairments such as delirium." (PMID 37904099, 2023). "Previous studies on animals revealed that metformin might enhance cognitive impairment by correcting the detrimental effects of inadequate insulin signaling, which leads to a chain reaction of unfavorable events including inflammation and tau hyperphosphorylation." (PMID 38139841, 2023). "On the other hand, in animals with impaired insulin signaling, had imbalanced oxidants and antioxidants (oxidative stress) and reduced expression of synaptic proteins in the hippocampus, which might have led to cognitive impairment in them." (PMID 38260013, 2023). "As a result, the use of INI, which activates the insulin system in the brain, may be useful for preventing cognitive deficits in patients with DM, as well as for restoring the central insulin-mediated regulation of peripheral metabolism and physiological functions." (PMID 36834685, 2023). "The interaction between insulin signaling and AD or cognitive impairment can be also demonstrated by research data showing improvements in the cognitive function of AD patients after the administration of antidiabetic drugs such as intranasal insulin, metformin, thiazolidinediones, and incretins." (PMID 35563031, 2022). "Thus, the possibility exists that AP efficacy to target cognitive deficits may be diminished secondarily via AP-induced metabolic dysregulation and insulin resistance." (PMID 36441736, 2022). "Notably, it was found that defective insulin signaling in the brain of AD patients may contribute to synaptic damage and cognitive deficits, and that normalization of insulin signaling may be beneficial." (PMID 36712676, 2022). "Cognitive dysfunction in SCZ may also be associated with central insulin deficits, which involve the regulation of dopamine, glucose metabolism and feeding, and exercise or pharmacological interventions to improve insulin sensitivity may be one way to address cognitive deficits in SCZ." (PMID 36406755, 2022). "However, T2D and excess caloric intake are also risk factors for developing cognitive deficits and AD, and the exact molecular mechanisms linking insulin resistance to AD are not currently well characterized." (PMID 33845179, 2021). "As previously reported, Akkermansia preserves colonic barrier permeability, reduces blood endotoxin levels, improves insulin resistance, and protects AD model mice from cognitive deficits and amyloid pathology, indicating that it may slow the progression of AD." (PMID 34745305, 2021). "Indeed, the intranasal treatment of insulin has been proved could attenuate the symptoms in AD and mild cognitive impairment." (PMID 33461175, 2021). "Thus β-glucan might exhibit its ability against HFFD-induced cognitive impairment by lowering neuroinflammation and restoration of insulin signaling and Tau neuronal proteins for synaptogenesis." (PMID 33008466, 2020). "Finally, using animal models of chemobrain and in vivo models of cognitive impairment, we previously showed that insulin signaling could be one of the factors mediating the cognitive dysfunction in chemobrain." (PMID 32156040, 2020). "Hence, these results further support the hypothesis that cognitive deficits in DS might be mediated by the dysfunction of insulin signaling in the brain." (PMID 32733190, 2020). "Since the hippocampus is integral to many forms of learning and memory and neural insulin signaling facilitates hippocampal-dependent memory, the authors hypothesized that a high fructose diet may contribute to cognitive impairment by impairing the brain insulin signaling pathway." (PMID 33374894, 2020). "However, T3D-959 treatment, an orally active brain-penetrating PPARδ/γ dual nuclear receptor agonist and a potent insulin sensitizer, ameliorated cognitive deficits and AD pathological hallmarks via promoted expression of insulin/IGF-1/Akt signaling proteins in the temporal lobes." (PMID 32719587, 2020).